KAT2A (lysine acetyltransferase 2A)
Diseases named in the same sentence as KAT2A in open-access papers (continued):
Sharing a sentence is not in itself a finding about the gene and the disease.
lung carcinoma (3 papers, 2016 to 2020). "KAT2A over expression increases the extent of histone acetylation by interacting with E2F1, cyclin D1, and E1 promoters to promote the proliferation of lung cancer cell lines." (PMID 31828117, 2019). "DDIT3 cooperates with KAT2A to up-regulate TNFRSF10A and TNFRSF10B expressions and to induce the endoplasmic reticulum stress-mediated apoptosis in lung cancer." (PMID 27931220, 2016).
neuroblastoma (3 papers, 2023 to 2025). Neuroblastoma (NB) is the most common solid, extracranial childhood tumor. "On the basis of our findings using the PROTAC degrader GSK-699-1, combined loss of KAT2A/KAT2B reduced neuroblastoma proliferation and induced transcriptional and epigenetic changes that are consistent with TADA2B degradation." (PMID 38820154, 2024). "We report that the acetyltransferase activity of the SAGA complex is required to maintain the oncogenic state in neuroblastoma and that impairing this activity either through TADA2B KO/degradation or through combined loss of KAT2A/KAT2B impairs neuroblastoma cell growth." (PMID 38820154, 2024). "We used GSK983, a small molecule degrader optimized for drug-like properties, to target the transcriptional coactivator KAT2A in MYCN-driven neuroblastoma." (PMID 40274766, 2025). "In conclusion, our study has unveiled a previously unrecognized feedforward loop between MYCN and KAT2A that orchestrates an oncogenic transcriptional program in neuroblastoma." (PMID 40274766, 2025). "We generated neuroblastoma cell lines expressing this construct and knocked out endogenous KAT2A using CRISPR-Cas9 with an sgRNA that spans an intron/exon junction and therefore cannot cut the exogenous cDNA of KAT2A." (PMID 38820154, 2024). "The SAGA acetyltransferase complex is required to promote neuroblastoma growth and is targetable with a KAT2A/KAT2B PROTAC." (PMID 38820154, 2024). "We then knocked out KAT2B with two distinct sgRNAs and found that KELLY cells were now more sensitive to KAT2A degradation, indicative of functional redundancy between these two paralogs in neuroblastoma." (PMID 38820154, 2024). "Targeting KAT2A could provide a new strategy to block MYCN’s oncogenic activity in neuroblastoma." (PMID 37777587, 2023). "Here we postulate a potential role for KAT2A in MYCN-mediated transcription and the potential for KAT2A inhibition as an anti-MYCN therapy for neuroblastoma." (PMID 40274766, 2025). "Further, the impact of pharmacologic degradation of KAT2A/KAT2B strongly correlated with the impact of TADA2B degradation, supporting the importance of the SAGA complex in maintaining MYCN-amplified neuroblastoma." (PMID 38820154, 2024). "To interrogate the possibility that KAT2A and KAT2B are functionally redundant in this context, we used two MYCN-amplified neuroblastoma cell lines, KELLY and NB1, that depend on TADA2B but have high and low KAT2B expression, respectively." (PMID 38820154, 2024). "In this study, we have assessed disulfiram’s effects on neuroblastoma using in vitro and in vivo models, focusing on how it modulates the neuroblast transcriptome and epigenome, particularly via MYCN and KAT2A." (PMID 37777587, 2023). "On the basis of our previous data showing that simultaneous KAT2A/KAT2B loss reduced neuroblastoma viability, we hypothesized that the KAT2A/KAT2B PROTAC, GSK-699, may be a pharmacologic intervention for MYCN-amplified neuroblastoma." (PMID 38820154, 2024). "Together, these data suggest that therapeutic targeting of the SAGA complex via degradation of KAT2A and KAT2B may be a therapeutic strategy for MYCN-amplified neuroblastoma." (PMID 38820154, 2024).
pancreatic ductal adenocarcinoma (3 papers, 2021 to 2025). An infiltrating adenocarcinoma that arises from the epithelial cells of the pancreas. "Investigations have revealed that KAT2A is not only abundantly manifested in human pancreatic ductal adenocarcinoma but also displays a positive correlation with the progressed stages of pancreatic ductal adenocarcinoma and a diminished patient survival rate." (PMID 39278916, 2024). "KAT2A is also highly expressed in human pancreatic ductal adenocarcinoma (PDAC) specimens and positively correlated with advanced stages of PDAC and short patient survival." (PMID 34149798, 2021). "Histone succ orchestrated by KAT2A might be a key player in disease pathogenesis, as seen in the emergence of human pancreatic ductal adenocarcinoma (PDAC) and in the context of Hepatitis B virus infection." (PMID 39278916, 2024).
renal cell carcinoma (3 papers, 2021 to 2026). "This study aims to investigate the underlying mechanisms of KAT2A/MCT1 axis in renal cell carcinoma (RCC), providing potential therapeutic targets." (PMID 34268311, 2021).
systemic lupus erythematosus (3 papers, 2021 to 2023). An autoimmune multi-organ disease typically associated with vasculopathy and autoantibody production. "A recent work found that in systemic lupus erythematosus (SLE), KAT2A was abnormally upregulated, and modulated the expression and acetylation of cyclic GMP‐AMP synthase." (PMID 37313329, 2023). "Although inhibition of KAT2A in PBMCs derived from lupus patients can inhibit interferon secretion, overexpression of KAT2A in monocyte lines could not significantly increase interferon secretion based on our data." (PMID 34718330, 2021).
asthma (2 papers, 2019 to 2025). "Moreover, five additional genes (KAT2A, HIST1H1C, NFRKB, C14orf178 and ZNF213-AS1) were suggestively associated with asthma (P < 0.0001) from the regular Omnibus-Fisher test." (PMID 31063461, 2019).
brain tumor (2 papers, 2025). "KAT2A has been shown to interact with ACSS2 to promote brain tumor growth and immune evasion." (PMID 41225436, 2025). "Moreover, KAT2A has been identified as a lactyltransferase that catalyzes histone H3 lactylation, thereby promoting PD-L1 expression and driving tumor growth and immune evasion in brain tumors." (PMID 41225436, 2025).
breast tumor (2 papers, 2024 to 2026). "To define whether STAT3 directly regulates Kat2a expression we next performed ChIP-qPCR in 4T1 and EMT6.5 breast tumor spheroids with and without extra palmitate." (PMID 41826695, 2026).
clear cell renal cell carcinoma (2 papers, 2021 to 2024). "Notably, lysine acetyltransferase 2A (KAT2A) expression is markedly increased in clear cell renal cell carcinoma (ccRCC), where it likely promotes tumour metastasis and proliferation by modulating the immune‐suppressive tumour microenvironment." (PMID 39428564, 2024). "We obtained the expression data of KAT2A and MCT1 from The Cancer Genome Atlas Kidney Clear Cell Carcinoma (TCGA-KIRC) and International Cancer Genome Consortium (ICGC) databases." (PMID 34268311, 2021).
diabetic cardiomyopathy (2 papers, 2024 to 2026). Diabetic cardiomyopathy is a disorder of the heart muscle in people with diabetes. "In diabetic cardiomyopathy (DCM), lysine acetyltransferase 2a (Kat2a) triggers ferroptosis by enhancing histone acetylation at the promoter regions of TfR1 and Hmox1, unveiling a previously unrecognized role of the Kat2a/Hmox1/TfR1 signaling axis." (PMID 41550269, 2026).
kidney cancer (2 papers, 2021). Primary or metastatic malignant neoplasm involving the kidney. "Previous studies have already indicated that aberrant KAT2A was associated with aggressive phenotypes across various tumors, however, its specific effect in kidney cancer still remains unclear." (PMID 34268311, 2021). "Given the previous results that a high KAT2A correlated with the clinical risk parameters and overall survival (OS) in RCC, no current studies uncovered the underlying mechanisms between KAT2A and oncogenic phenotypes in kidney cancer." (PMID 34268311, 2021). "However, KAT2A was not significantly up-regulated in 800 samples based on GEO and EBI database, and EP300 was significantly up-regulated in kidney cancer, PRAD and TGCT." (PMID 34136387, 2021).
melanoma (2 papers, 2023). A malignant, usually aggressive tumor composed of atypical, neoplastic melanocytes. "Melanoma cells with TRIM22 deficiency depended on KAT2A to enhance malignant progression, including proliferation, migration, and in vivo growth." (PMID 37415153, 2023). "TRIM22 deficiency mediates the accumulations of KAT2A and depended on KAT2A to promote melanoma progression." (PMID 37415153, 2023). "The KAT2A is a bona fide target of TRIM22, and TRIM22 deficiency promoted the accumulation of KAT2A proteins in melanoma." (PMID 37415153, 2023). "Together, our study revealed the novel role of the TRIM22/KAT2A axis in modulating melanoma progression and provided essential targets for treatment." (PMID 37415153, 2023). "Together, our study illustrates the mechanism by which the TRIM22-KAT2A-Notch1 axis promotes melanoma progression, and demonstrates that KAT2A/Nocth1 confers an epigenetic vulnerability in TRIM22low melanoma." (PMID 37415153, 2023). "TRIM22 mediates the ubiquitination and degradation of KAT2A proteins in melanoma." (PMID 37415153, 2023). "KAT2A mediates the activation of Notch1 signaling to maintain the stemness features of melanoma." (PMID 37415153, 2023). "KAT2A activates Notch1 transcriptional levels and sustains the stemness feature of melanoma cells." (PMID 37415153, 2023). "The Chromatin Immunoprecipitation (ChIP)-seq and Assay for Transposase-Accessible Chromatin with high-throughput Sequencing (ATAC-seq) analysis of KAT2A are warranted to be performed in the future to thoroughly determine the epigenetic roles of KAT2A in melanoma." (PMID 37415153, 2023). "For instance, by demonstrating that the inhibition of KAT2A downregulates BETi resistance-related pathways and sensitizes melanoma to BETis, our research suggests a potential strategy to enhance the effectiveness of BETi treatment in melanoma patients." (PMID 37513949, 2023).
Arthritis (1 paper, 2023). Inflammation of a joint. "The mRNA expression of Kat2a in synovial macrophages from CIA model was also significantly higher after arthritis induction, which was strongly correlated with Nlrp3 expression in synovial macrophages." (PMID 37313329, 2023). "With the progress of arthritis, both mRNA and protein expression of KAT2A in synovial tissue samples of CIA model was remarkably increased, consistent with the phenomenon in human RA patients." (PMID 37313329, 2023). "Administration of MB‐3, the KAT2A‐specific chemical inhibitor, significantly ameliorated the synovitis and bone destruction in collagen‐induced arthritis model." (PMID 37313329, 2023). "Kat2a mRNA expression in synovial macrophages from CIA model was obviously higher after arthritis induction." (PMID 37313329, 2023). "Furthermore, Kat2a expression was strongly correlated with Il1b expression in synovial macrophages and clinical score of arthritis mice." (PMID 37313329, 2023). "Nevertheless, it could not exclude whether KAT2A had the regulatory role in other pathogenic immune cells for arthritis." (PMID 37313329, 2023). "In addition, we focused the proinflammatory effects of KAT2A in macrophage‐mediated arthritis." (PMID 37313329, 2023). "In this way, we speculated whether KAT2A played a role in NLRP3 gene expression in inflammatory macrophages and arthritis." (PMID 37313329, 2023).
Ataxia (1 paper, 2020). Ataxia refers to impaired coordination of voluntary muscle movement. "Consistently, conditional deletion of Kat2a/Gcn5 in Purkinje cells of wild type mice does not lead to severe ataxia." (PMID 32581696, 2020).
autoimmune disease (1 paper, 2023). A disorder resulting from loss of function or tissue destruction of an organ or multiple organs, arising from humoral or cellular immune responses of the individual to their own tissue constituents. "In autoimmune disease, KAT2A could catalyze histone H3 lysine H9 acetylation to induce the IL2 expression and modulate T cell immunity." (PMID 37415153, 2023).
B cell lymphoma (1 paper, 2024). "In the context of B cell lymphoma, however, loss of KAT2A activity alone had a significant impact on disease progression in a mouse model." (PMID 38820154, 2024).
bacterial meningitis (1 paper, 2026). Inflammation of the membranes surrounding the brain and spinal cord due to a bacterial infection. "Collectively, these findings reveal the underlying mechanism by which SC19 disrupts BBB through inducing KAT2A-mediated necroptosis and provide a potential therapeutic target for the treatment of bacterial meningitis." (PMID 41882776, 2026).
breast invasive carcinoma (1 paper, 2025). "KAT2A exhibited significantly higher expression in various tumors, including bladder urothelial carcinoma (BLCA), breast invasive carcinoma (BRCA), and other malignancies." (PMID 41225436, 2025).
Burkitt lymphoma (1 paper, 2019). A rare form of malignant mature B-cell non-Hodgkin lymphoma. "We found that GCN5 (KAT2A) mRNA is overexpressed in certain lymphomas, and especially in Burkitt lymphomas, which have high expression of MYC." (PMID 31645904, 2019).
Cerebral ischemia (1 paper, 2024). Restriction of arterial blood supply to the brain associated with insufficient oxygenation to support the metabolic requirements of the tissue. "Collectively, our findings indicated that the neuroprotective effect of CAT against cerebral ischemia was associated with the inhibition of autophagy via the NRF1/KAT2A/METTL3/Beclin-1 axis." (PMID 38773376, 2024). "A prior study reported that KAT2A played a protective role in myocardial ischemia–reperfusion; however, its role in cerebral ischemia remains to be disclosed." (PMID 38773376, 2024). "Moreover, bioinformatics data and experimental results implied that NRF1 activated METTL3 transcription via KAT2A, which assumed a neuroprotective role in cerebral ischemia." (PMID 38773376, 2024). "Overall, NRF1 activated METTL3 transcription via KAT2A, which may play a protective role in cerebral ischemia." (PMID 38773376, 2024). "However, the role of KAT2A in cerebral ischemia remains to be studied." (PMID 38773376, 2024). "As a result, the present study revealed that CAT, the main active component of Rehmannia, protected against cerebral ischemia in vivo and in vitro by inhibiting neuronal injury and autophagy via the NRF1/KAT2A/METTL3/Beclin-1 axis." (PMID 38773376, 2024). "CAT activated the NRF1/KAT2A/METTL3 axis and downregulated Beclin-1 expression, thus relieving neuronal injury and excessive autophagy after cerebral ischemia." (PMID 38773376, 2024). "On this basis, we conjectured that NRF1 may activate METTL3 transcription by promoting KAT2A transcription and increasing H3K27 acetylation level in METTL3 promoter region, thus playing a protective role in cerebral ischemia." (PMID 38773376, 2024). "Accordingly, we analyzed the mechanism of CAT in cerebral ischemic via the NRF1/KAT2A/METTL3/Beclin-1 axis with the focus on neuronal injury and autophagy, aiming to offer a theoretical basis for the development of CAT as neuroprotective drugs for the prevention and treatment of cerebral ischemia." (PMID 38773376, 2024).
cervical cancer (1 paper, 2019). A primary or metastatic malignant neoplasm involving the cervix. "KAT2A knockdown leads to a significant reduction of DNA synthesis in cervical cancer cells by decreasing histone H3 acetylation in the E2F1 promoter." (PMID 31828117, 2019).
childhood cancer (1 paper, 2025). "Further investigation and clinical development of KAT2A-targeted therapies hold the potential to make a significant impact on the management of this aggressive childhood cancer." (PMID 40274766, 2025).
chordoma (1 paper, 2013). Chordomas are rare malignant tumors arising from embryonic remnants of the notochord in axial skeleton. "Six genes (NOTCH2, NCOR2, CREBBP, JAG1, KAT2A and NCSTN) related to the Notch signaling pathway were upregulated in chordoma tissues." (PMID 23826111, 2013).
ductal carcinoma (1 paper, 2021). "e The patients with ductal carcinoma (n = 1863) were filtrated for genetic alterations analysis of CREBBP and KAT2A genes." (PMID 33827682, 2021).
endometriosis (1 paper, 2024). The growth of functional endometrial tissue in anatomic sites outside the uterine body. "To further validate the interaction between KAT2A and ENO1 in endometriosis progression, we transfected ESCs with sh-KAT2A and ENO1 overexpressing plasmid and tested the biological functions of ESCs." (PMID 38585644, 2024). "In summary, we found that succinylation of ENO1 mediated by KAT2A played a role in promoting the progression of endometriosis." (PMID 38585644, 2024). "In summary, we confirmed the high expression of KAT2A in endometriosis and its deteriorating effect on ESCs." (PMID 38585644, 2024). "In vitro experiments showed that KAT2A silencing inhibited the migration and invasion of ESCs, suggesting that KAT2A promotes the malignant development of endometriosis." (PMID 38585644, 2024). "In our future studies, more cell lines will be used, and we will conduct animal experiments to further explore the specific mechanisms of KAT2A in endometriosis." (PMID 38585644, 2024). "In the present study, we confirmed the upregulation of succinate transferase KAT2A in endometriosis." (PMID 38585644, 2024). "Therefore, we further tested whether KAT2A was involved in the regulation of ENO1 to reveal its biological mechanism in the development of endometriosis." (PMID 38585644, 2024). "However, there is no research confirming whether KAT2A can regulate ENO1 and reduce the condition of patients with endometriosis." (PMID 38585644, 2024).
experimental arthritis (1 paper, 2023). ARTHRITIS that is induced in experimental animals. "Here, we found that increased expression of lysine acetyltransferase 2A (KAT2A) in synovial tissues was closely correlated with inflammatory joint immunopathology in both RA patients and experimental arthritis mice." (PMID 37313329, 2023).
Fanconi anemia (1 paper, 2025). Fanconi anemia (FA) is a hereditary DNA repair disorder characterized by progressive pancytopenia with bone marrow failure, variable congenital malformations and predisposition to develop hematological or solid tumors. "Six hub genes (FANCI, KAT2A, TACC3, TPX2, VHL, WSB1) were enriched in Fanconi anemia and HIF-1 pathways, affecting microtubules, spindle formation, and cytoskeleton dynamics during mitosis." (PMID 40832468, 2025).
Hutchinson-Gilford progeria (1 paper, 2024). "A previous discovery showed that electromagnetic stimulation activated KAT2A, which increased hippocampal neurogenesis in aged and Hutchinson-Gilford progeria mouse brains, thereby remitting the symptoms of aging." (PMID 38773376, 2024).
intestinal cancer (1 paper, 2022). "KAT2A, succinylate, and succinyltransferase could decrease the α-KGDH complex entered the nucleus, reduce the gene expression, and inhibit the cell proliferation and growth in intestinal cancers." (PMID 35928108, 2022).
medulloblastoma (1 paper, 2022). A malignant, invasive embryonal neoplasm arising from the cerebellum. "The RNA-seq results from Fsmo;hGFAP-Cre medulloblastomas showed significant downregulation of histone acetyltransferases (HAT: Hat1 and Kat2a/GCN5), the histone deacetylase (HDAC) Hdac1, and the histone acetylation reader Brd2 between vehicle- and LDE-treated samples." (PMID 36688010, 2022).
myocardial ischemia (1 paper, 2024). A disorder of cardiac function caused by insufficient blood flow to the muscle tissue of the heart. "A related study revealed that KAT2A played a protective role in myocardial ischemia–reperfusion." (PMID 38773376, 2024).
non-Hodgkin lymphoma (1 paper, 2023). Distinct from Hodgkin lymphoma both morphologically and biologically, non-Hodgkin lymphoma (NHL) is characterized by the absence of Reed-Sternberg cells, can occur at any age, and usually presents as a localized or generalized lymphadenopathy associated with fever and weight loss. "Similarly, KAT2A was found to be positive in non-Hodgkin’s lymphoma in HPA." (PMID 37789275, 2023).